IL1B (interleukin 1 beta)
Diseases named in the same sentence as IL1B in open-access papers (continued):
Sharing a sentence is not in itself a finding about the gene and the disease.
Hyperglycemia (continued). "In the present work we assessed mRNA expression and serum protein levels of IL-1β in newly diagnosed T2D individuals with hyperglycemia and after 6 and 12 months of treatment, when they achieved their glycemic target control." (PMID 32561825, 2020). "There is evidence that hyperglycemia, ER stress, and oxidative stress induce IL-1β secretion from β-cells and macrophages through activation of the NLRP3 inflammasome." (PMID 33457426, 2020). "It looks like hyperglycemia stimulates human pancreatic β-cells to produce IL-1β, mediating by this way β-cell dysfunction, cell death, worsened hyperglycemia, and inflammatory cycle propagation." (PMID 33172097, 2020). "Human retinal pigment epithelial cells (ARPE-19) were stimulated with hyperglycemia and the inflammatory cytokines IL-1β and TNFα in order to mimic diabetic retinopathy molecular signs in vitro." (PMID 33396676, 2020). "Since hyperglycemia is known to increase levels of pro-inflammatory cytokines such as IL-1β and TNF-α in the diabetic retina, these factors presumably exert their effect on neuritogenesis as observed in our study." (PMID 31607843, 2019). "Treatment of Nrf2 activator DMF (HG/DMF) partly restored hyperglycemia-induced expression of IL1β and IL6, while it completely restored MCP1 expression compared to the HG/VEH group." (PMID 31616304, 2019). "Hyperglycemia can yield inflammation and can induce renal injury by promoting IL-1β and caspase-1 expression in renal cells." (PMID 31119177, 2019). "Real-time PCR demonstrated that ARPE-19 cells responded to either cytokines or hyperglycemia by upregulating proinflammatory genes such as cytokines (IL-1β and IL-6) and chemokines (CCL2, CCL5) as well as VEGF, an established inducer of vascular leakage." (PMID 31344857, 2019). "In primary cultured human brain microvascular endothelial cells (HBMEC), hyperglycemia (25 mM glucose) plus interleukin 1 beta (20 ng/ml) (HG-IL1β) served as T2DM insult in vitro." (PMID 31101061, 2019). "Of note, FGF21 has been shown to reduce levels of inflammatory mediators including IL-1β, IL-6 and TNFα in the serum of obese/diabetic db/db mice and ameliorates hyperglycemia." (PMID 31312114, 2019). "Hyperglycemia increases the expression of pro-inflammatory cytokines such as IL-6, IL-1β, TNF-α, and TGF-β." (PMID 31736745, 2019). "Heme oxygenase 1 overexpression suppresses hyperglycemia-induced gene expression of IL1β, IL6, and MCP1." (PMID 31616304, 2019). "The results showed that hyperglycemia treatment (HG/VEH) significantly increased the secretion of IL1β, IL6, and MCP1 to 261%, 311%, and 156%, respectively, compared to the LG/EMP group." (PMID 31616304, 2019). "Hyperglycemia plays a key role in the development of this disorder, inducing oxidative stress and release of several cytokines such as IL-1β, TNF-α, TGF-β1, which promote myocardial cell death and fibrosis." (PMID 31835864, 2019). "Previous studies also demonstrated that advanced glycosylation ends triggered by long-term hyperglycemia can stimulate phagocytes to release inflammatory cytokines, including tumor necrosis factor, IL-1β, and IL-6." (PMID 31209719, 2019). "The data in this article is associated with the research article published in Biochim Biophys Acta “Acute pancreatic beta cell apoptosis by IL-1β is responsible for postburn hyperglycemia: evidence from humans and mice”." (PMID 30555869, 2018). "It has been established that ER stress can induce inflammasome activation and mature IL-1β secretion either by using chemical ER stress inducers or under hyperglycemia or hyperlipidemia conditions." (PMID 29844315, 2018). "BAY 11-7082 protects rats from DN by reducing the expression of inflammatory cytokines including TNF-α, IL-1β, and IL-6, and inhibiting the oxidative damage mediated by hyperglycemia." (PMID 30459606, 2018).
Hyperglycemia (continued). "In recent years, free fatty acid-bound fetuin-A has been shown to be an endogenous ligand for toll-like receptor 4 (TLR4), and hyperglycemia has been shown to enhance IL-1β secretion." (PMID 28299342, 2017). "Ca2+ influx was known to be a critical regulator of lysosomal exocytosis to mediate IL-1β secretion, and prolonged hyperglycemia was known to be resulted in Ca2+ influx and an increase in [Ca2+]i in different cell types." (PMID 28970837, 2017). "Our previous study demonstrated that hyperglycemia, a hallmark characteristic of T2DM, induced NLRP3 inflammasome-dependent caspase-1 activation and IL-1β maturation in human monocytic cells." (PMID 28970837, 2017). "Hyperglycemia induced by glucose clamping in normal subjects showed a significant increase in the circulating levels of interleukin- (IL-) 6, IL-18, Il-1β, and tumor necrosis factor-α (TNF-α)." (PMID 27034691, 2016). "A recent study indicated that hyperglycemia induced NF-κB activation leading to an increase in inflammatory cytokines, IL-1β and TNF-α level, in diabetic kidneys and an increase in TGF-β1 gene expression in STZ-induced diabetic rats." (PMID 27649140, 2016). "Hyperglycemia stimulates the secretion of macrophage-produced cytokine IL-1β, which induces inflammatory cytokine production and invasion into renal tissues." (PMID 26881256, 2016). "Recent work demonstrated that TXNIP induced NLRP3 expression, activation of caspase-1, and release of IL-1β in a model of hyperhomocysteinemia or hyperglycemia with podocyte injury." (PMID 27867451, 2016). "The neutrophils from the CCR2 KO or DEREG chimeric mice with hyperglycemia showed enhanced expression of IL-1β and TNF-α compared with those from the control mice." (PMID 27464894, 2016). "Multiple cytokines and chemokines relevant to diabetic complications are induced by hyperglycaemia, including interleukin-1 beta (IL-1β)." (PMID 25950006, 2015). "At the end of 24 hr, hyperglycemia augmented the mRNA expressions of interleukin (IL)-1β and IL-6 in the MLNs, while both the helper T (Th) 2 and regulatory-T (Treg) transcriptional factors were simultaneously up-regulated under non-endotoxemic condition." (PMID 26207186, 2015). "It was also found that hyperglycemia yielded the IL-1β production from human islet β-cells, resulting in decreased β-cell proliferation, increased β-cell dysfunction and apoptosis." (PMID 26394923, 2015). "On one hand, excessive IL-1β was found produced by T cells and pancreatic β-cells under circumstance of hyperglycemia; on the other hand, the elevated IL-1β induced apoptosis of β-cells to further impair insulin secretion." (PMID 26394923, 2015). "Hyperglycemia induces the production of IL-1β, which interferes with insulin signaling and has cytotoxic effects on beta cells, leading to impaired insulin secretion." (PMID 25053966, 2014). "Consistently, in cultured cardiomyocytes incubated with 30 mmol/l or 50 mmol/l glucose (HG) to mimic hyperglycemia, IL-1β and IL-18 levels were also found significantly increased, indicating an induction of cardiomyocyte pyroptosis." (PMID 25341033, 2014). "At the onset of hyperglycemia, the levels of IL-1β and inflammatory responses such as TLR4, COX1, COX2, NF-κB, CD45, and iNOS were increased in the hippocampus." (PMID 22844396, 2012). "Previous evidence has also suggested that hyperglycemia induces NF-κB activation as a result of increased levels of IL-1β." (PMID 22844396, 2012). "On the other hand, the innate immune response to chronic hyperglycemia by IL-1β, NLRP3 and caspase-1 inflammasome is cyclical." (PMID 22474421, 2012). "In addition, the concentrations of serum NF-κB p-p65, IL-1β, and IL-10 in all animals were measured by ELISA to further evaluate the expression of inflammatory factors in chickens and rats with hyperglycemia induced by STZ." (PMID 41463431, 2025).
Hyperglycemia (continued). "During hyperglycemia, ROS also stimulates VSMCs to release IL-1, Interleukin 6 (IL-6), Interleukin 1 beta (IL-1β), TNFα, histamine, and bradykinin, which disrupt the junctions between endothelial cells, increase permeability, and thereby facilitate the passage of monocytes and oxLDL." (PMID 40362167, 2025). "In addition, upstream inhibition of the caspase-1/IL-1β signaling using YVAD-fmk or RIP2 knock down also prevented hyperglycemia mediated cell death of Müller cells." (PMID 39483336, 2024). "IL-1β promotes inflammation and impairs insulin signaling, worsening hyperglycemia." (PMID 39840100, 2024). "Studies have unveiled specific mechanisms contributing to post-burn hyperglycemia, including IL-1β-induced pancreatic β-cell apoptosis, endoplasmic reticulum (ER) stress leading to islet dysfunction, and an imbalance in mitochondrial reactive oxygen species (ROS) production in islet cells." (PMID 39830385, 2024). "Existing hyperglycaemia during GDM, due to insulin insufficiency, is known to cause certain immune dysfunction that leads to leukocyte dysfunction and the increased production and secretion of cytokines, like IL-1β, IL-6 and TNF-α." (PMID 39518962, 2024). "Interestingly, although caspase-1 activation during this feedback signaling is mediated by two distinct stimuli, hyperglycemia and IL-1β, both pathways are controlled by one regulator, RIP2." (PMID 39483336, 2024). "Moreover, it is thought that the oxidative stress brought on by hyperglycemia raises the number of cytokines like IL-1β, TNFα, IL-6, and IL-10 that promote inflammation." (PMID 39328924, 2024). "Hyperglycemia, dyslipidemia, insulin resistance, and obesity upregulate the expression of MR, which elevates inflammatory (IL-1β, IL-6, TNF-α, MCP-1) and profibrotic factors (extracellular matrix proteins, PAI-1, TGF-β, CTGF), eventually resulting in the progression of DKD." (PMID 38542060, 2024). "In addition, activation of caspase-1 by both stimuli, hyperglycemia and IL-1β, was mediated by RIP2 as determined by RIP2 knockdown experiments." (PMID 39483336, 2024). "Due to postprandial hyperglycemia and hyperlipidemia, there is an increase in circulating pro-inflammatory cytokines (IL-1β, TNFα and IL-6) in the blood, which originate from adipose tissue and connective tissue cells and promote chronic low-grade inflammation." (PMID 38137918, 2023). "Maternal hyperglycemia leads to excessive production of proinflammatory cytokines in the placenta and directly affects the fetus, and neonatal hyperglycemia also promotes the production of interleukin 1β (IL-1β), tumor necrosis factor α (TNF-α) and toll-like receptor activity in spleen cells." (PMID 37735200, 2023). "Therefore, our goal is to evaluate the effects of chronic hyperglycemia and insulin treatment on IL1β immunoreactivity in myenteric neurons and their different subpopulations along the duodenum–ileum–colon axis." (PMID 36982878, 2023). "In fact, it has been reported that pro-inflammatory cytokines (e.g., TNFα, interleukin 1β (IL-1β), interleukin 18 (IL-18) and IL-6) are increased in acute hyperglycemia, whereas in the opposite condition, when insulin is working, these cytokines are significantly decreased." (PMID 38137918, 2023). "In addition, morphological signs of microglial response to hyperglycemia, as well as increased pro-inflammatory mediators, such as IL-1β, CCL2 and TNF-α, were described." (PMID 36869375, 2023). "We showed that hyperglycemia enhanced the proinflammatory response of M(IFNγ) to Hb-Hp complex uptake by stimulating the production of TNFα, IL-1β, IL-6, IL-8, and IL-1RA, supporting the observation that hyperglycemia itself can induce the secretion of proinflammatory cytokines." (PMID 35163309, 2022).
Hyperglycemia (continued). "Hyperglycemia is associated with both conditions of oxidative stress and inflammatory state and promotes mitochondrial metabolism in β cells which enhances the production of ROS, thus inducing NLRP3 inflammasome activation and then IL-1β production." (PMID 35276849, 2022). "Additionally, serum miR-10a, miR-21, miR-33a, miR-125a, and miR-146a levels were positively correlated with TC, TG, LDL-c, CRP, and IL-1β levels in individuals with hyperglycemia and hyperlipidemia." (PMID 36355127, 2022). "TFP5 treatment decreased hyperglycemia-induced IL-6, IL-1β, and TNF-α upregulation." (PMID 35874807, 2022). "Moreover, in the pathological state of hyperglycemia and hemodynamic disorder, a large number of renal macrophages are infiltrated, and multiple inflammatory cytokines such as IL-1β, TNF-α, and IL-6 are released." (PMID 35355720, 2022). "Our experimental model of hyperglycemia resulted in a visible alteration of the HuASCs immunomodulatory properties and triggered an augmentation of the pro-inflammatory marker expression, including IL-1β and TNF-α at both the mRNA and the proteins levels." (PMID 35327652, 2022). "Additionally, our results showed that BA treatment significantly ameliorated hyperglycemia-mediated NFκB p65 transcriptional activation, subsequently decreasing the release of pro-inflammatory cytokines, including IL1β, IL6 and MCP1." (PMID 35415192, 2022). "Moreover, hyperglycemia drives IL-1β production in obesity through activation of the thioredoxin-interacting protein." (PMID 35307018, 2022). "Exposure of INS-1E cells to high glucose concentration to mimic chronic hyperglycemia (30 mM glucose for 48 h) or pro-inflammatory conditions (cytomix: 10 U/ml IL-1β, 500 U/ml TNF-α, and 100 U/ml IFN-γ for 24 h) led to a ~2-3 fold increase in REV-ERBα protein expression (P < 0.05 and P < 0.001)." (PMID 35428762, 2022). "IL-1β damages retinal capillary endothelial cells by activating NF-κB and increasing oxidative stress, which can mediate mitochondrial damage, and it accelerates this damaging process in the case of hyperglycemia." (PMID 36582230, 2022). "The pro-inflammatory environment resulting from hyperglycemia and/or insulin resistance is the result of the higher expression of inflammatory mediators, such as IL-1β, IL-6, TNF-α, TGF-β, IKKβ, and JNK, that may have local or systemic action." (PMID 36552014, 2022). "To verify the observation in IL-1β mRNA expression, we also assessed the IL-1β expression by ELISA using the cortex lysates, detecting a similar expression pattern with even a trend toward protein downregulation with hyperglycemia and glucosamine treatment." (PMID 36532524, 2022). "IL-1β and hyperglycemia may trigger apoptosis of beta cells, further contributing to the development of T2D." (PMID 35145521, 2022). "Because high expression of IL-1β in macrophages in the intestine can significantly promote chronic inflammation and aggravate the symptoms of hyperglycemia, we concluded that administration of BD3526 metabolites significantly inhibits the expression of IL-1β in macrophages in the intestine." (PMID 33424779, 2020). "In addition to the phenotypic changes, we also evaluated the bio-functional response in hyperglycemia-exposed macrophages by measuring secretion of critical proinflammatory proteins, such as IL-1β and MCP-1 (CCL2)." (PMID 32806763, 2020). "Our in vitro experimental results demonstrated that rFGF21 is strongly protective in hyperglycemia plus IL-1β -induced transendothelial permeability, which is FGFR1 activation-dependent and PPARγ activity-dependent, and also associated with the maintenance of junction protein expression." (PMID 32012810, 2020). "Therefore, IL-1β was found to be increased in stenotic aortic valves, with increased secretion induced by hyperglycemia, becoming a therapeutic target in patients with T2DM." (PMID 33255639, 2020).
Hyperglycemia (continued). "Our in vitro experimental results also demonstrated that rFGF21 protects against hyperglycemia plus interleukin (IL)-1β-induced transendothelial permeability through upregulation of junction protein expression in an FGFR1 activation and PPARγ activity elevation-dependent manner." (PMID 32012810, 2020). "As expected, these changes in protein expression were found to be concordant with the transcriptional modulations in cultured macrophages which displayed upregulated gene expression of M1 (CD11c, TNF-α, and IL-1β) and downmodulated M2 (IL-5) markers under constant or fluctuating hyperglycemia." (PMID 32806763, 2020). "Hyperglycemia (HG) plus IL-1β exposure was applied to mimic diabetic stroke conditions in vitro." (PMID 32012810, 2020). "Considering that hyperglycemia may have the same effects on ER and circulating monocytes, the decrease in glucotoxicity may favor the production of proteins such as IL-1β." (PMID 32561825, 2020). "Hyperglycemia triggers retinal ECs to upregulate the expression of IL-1β, which serves as an autocrine or paracrine to stimulate IL-1β expression in ECs or macroglial cells to a sustained overexpression of IL-1β." (PMID 33013692, 2020). "Moreover, according to the cytokine kit analysis, the VEGF, TNF-α, IL-18 and IL-1β levels in rat plasma demonstrated similar trends, which also supported that H3 relaxin lessened the inflammatory activity induced by hyperglycemia." (PMID 33584279, 2020). "Thus, we used hyperglycemia (25 mM glucose) plus IL-1β (20 ng/ml) (HG-IL1β) in HBMEC monolayer culture as an in vitro model of diabetic BBB insult." (PMID 31101061, 2019). "In conclusion, this study specifically identifies a decrease in bioactive IL-1β to possibly be, due to a deficit in intracellular processing rather than chronic hyperglycaemia, a strong candidate in the susceptibility of T1D patients to TB." (PMID 29189980, 2018). "Eventually, this could lead to the downregulation of IL-1β, which might mitigate retinal inflammation and protect the retina against hyperglycaemia-induced dysfunction." (PMID 29682582, 2018). "Concordantly, inhibition of IL-1β signalling using pharmacological or genetic approaches decreases caspase activity and apoptosis in retina, and prevents microvascular degeneration in hyperglycaemia-induced retinopathy models." (PMID 30089839, 2018). "Compared with a previous study in monocytes, both consistent and intermittent hyperglycemia increased a more dramatic production of the inflammatory cytokines TNF-α and IL-1β in macrophages, and this proinflammatory effect is more pronounced in response to intermittent hyperglycemia." (PMID 29850615, 2018). "This condition might be due to the release of the early neuropoietic cytokines like TNF-α, IL-1β, and IL-6 at the interphase of hyperglycemia induced biochemical changes and nerve damage." (PMID 28381989, 2017). "Given that hyperglycemia induces chronic inflammation as a causative factor of cardiac remodeling, the expression levels of inflammatory markers, including p-P38, p38, TNF-α, IL-1β, CARD9, and BCL10, were examined by Western blot." (PMID 28272348, 2017). "Moreover hyperglycemia is known to induce IL-1β expression in different immune cells leading to a pro-inflammatory macrophage phenotype proliferation and a persistent inflammatory response." (PMID 26757209, 2016). "However, metabolic defects, such as hyperglycemia and oxidative stress, induce excessive proinflammatory cytokines (IL-1β, TNF-α, etc.)production, sustaining a prolonged influx of neutrophils and macrophages." (PMID 27057551, 2016). "Indeed, suppression of chronic inflammation by blocking the IL-1β pathway improved hyperglycemia and β-cell secretory function in clinic." (PMID 25768847, 2015). "In a previous study, hyperglycemia over the level of 315 mg/dL could directly impair the functions of activated macrophages, resulting in up-regulation of the mRNA expressions of IL-1β and IL-6." (PMID 26207186, 2015).